PYCARD (PYD and CARD domain containing)
Description:
Functions as a key mediator in apoptosis and inflammation. Promotes caspase-mediated apoptosis involving predominantly caspase-8 and also caspase-9 in a probable cell type-specific manner. Involved in activation of the mitochondrial apoptotic pathway, promotes caspase-8-dependent proteolytic maturation of BID independently of FADD in certain cell types and also mediates mitochondrial translocation of BAX and activates BAX-dependent apoptosis coupled to activation of caspase-9, -2 and -3. Involved in innate immune response by acting as an integral adapter in the assembly of various inflammasomes (NLRP1, NLRP2, NLRP3, NLRP6, AIM2 and probably IFI16) which recruit and activate caspase-1 leading to processing and secretion of pro-inflammatory cytokines. Caspase-1-dependent inflammation leads to macrophage pyroptosis, a form of cell death. The function as activating adapter in different types of inflammasomes is mediated by the pyrin and CARD domains and their homotypic interactions. Clustered PYCARD nucleates the formation of caspase-1 filaments through the interaction of their respective CARD domains, acting as a platform for of caspase-1 polymerization. In the NLRP1 and NLRC4 inflammasomes seems not be required but facilitates the processing of procaspase-1. In cooperation with NOD2 involved in an inflammasome activated by bacterial muramyl dipeptide leading to caspase-1 activation. May be involved in RIGI-triggered pro-inflammatory responses and inflammasome activation. In collaboration with AIM2 which detects cytosolic double-stranded DNA may also be involved in a caspase-1-independent cell death that involves caspase-8. In adaptive immunity may be involved in maturation of dendritic cells to stimulate T-cell immunity and in cytoskeletal rearrangements coupled to chemotaxis and antigen uptake may be involved in post-transcriptional regulation of the guanine nucleotide exchange factor DOCK2; the latter function is proposed to involve the nuclear form. Also involved in transcriptional activation of cytokines and chemokines independent of the inflammasome; this function may involve AP-1, NF-kappa-B, MAPK and caspase-8 signaling pathways. For regulation of NF-kappa-B activating and inhibiting functions have been reported. Modulates NF-kappa-B induction at the level of the IKK complex by inhibiting kinase activity of CHUK and IKBK. Proposed to compete with RIPK2 for association with CASP1 thereby down-regulating CASP1-mediated RIPK2-dependent NF-kappa-B activation and activating interleukin-1 beta processing. Modulates host resistance to DNA virus infection, probably by inducing the cleavage of and inactivating CGAS in presence of cytoplasmic double-stranded DNA. [Isoform 2]: May have a regulating effect on the function as inflammasome adapter. [Isoform 3]: Seems to inhibit inflammasome-mediated maturation of interleukin-1 beta.
Synonyms: ASC; CARD5; TMS1; TMS-1; TMS
Tractability: Antibody: its Gene Ontology location is reachable by antibodies, with high confidence. PROTAC: UniProt records ubiquitination sites on it; ubiquitination databases record sites on it; its protein half-life has been measured.
Gene: Protein-coding gene on chromosome 16 (31,201,486 to 31,203,450, reverse strand). Ensembl gene ENSG00000103490.
Subcellular location: Cytoplasm; Inflammasome; Endoplasmic reticulum; Mitochondrion; Nucleus; Golgi apparatus membrane
Subcellular location (Human Protein Atlas): Nucleoplasm; Cytosol; Nucleoli
Pathways (Reactome):
Immune System: CLEC7A/inflammasome pathway; Neutrophil degranulation; The AIM2 inflammasome; The NLRP3 inflammasome
Disease: Purinergic signaling in leishmaniasis infection; SARS-CoV-1 activates/modulates innate immune responses
Gene Ontology:
Molecular function: BMP receptor binding; enzyme binding; identical protein binding; interleukin-6 receptor binding; myosin I binding; protease binding; protein binding; protein dimerization activity; protein homodimerization activity; protein-macromolecule adaptor activity; Pyrin domain binding; tropomyosin binding; cysteine-type endopeptidase activator activity; pattern recognition receptor activity; transmembrane transporter binding
Biological process: apoptotic signaling pathway; cellular response to interleukin-1; cellular response to lipopolysaccharide; cellular response to tumor necrosis factor; defense response to Gram-negative bacterium; defense response to virus; myeloid dendritic cell activation; negative regulation of canonical NF-kappaB signal transduction; negative regulation of cytokine production involved in inflammatory response; negative regulation of interferon-beta production; negative regulation of protein serine/threonine kinase activity; NLRP3 inflammasome complex assembly; positive regulation of adaptive immune response; positive regulation of apoptotic process; positive regulation of canonical NF-kappaB signal transduction; positive regulation of chemokine production; positive regulation of ERK1 and ERK2 cascade; positive regulation of extrinsic apoptotic signaling pathway; positive regulation of inflammatory response; positive regulation of interleukin-1 beta production; positive regulation of interleukin-10 production; positive regulation of interleukin-6 production; positive regulation of interleukin-8 production; and 33 more
Cellular component: AIM2 inflammasome complex; canonical inflammasome complex; cytoplasm; cytosol; endoplasmic reticulum; Golgi membrane; IkappaB kinase complex; mitochondrion; NLRP1 inflammasome complex; NLRP3 inflammasome complex; NLRP6 inflammasome complex; nucleolus; nucleoplasm; nucleus; protein-containing complex; azurophil granule lumen; extracellular region; microtubule; secretory granule lumen; neuronal cell body
Genetic constraint (gnomAD): Loss-of-function variants: 10 observed, 11.02 expected, observed/expected ratio (o/e) 0.91, 90% interval 0.56 to 1.53. The upper end of that interval is the gene's LOEUF score, 1.53, which puts it in group 6 of 6, group 1 being the genes least tolerant of losing a copy. Missense variants: 239 observed, 250.98 expected, observed/expected ratio (o/e) 0.95, 90% interval 0.86 to 1.06. Synonymous variants: 121 observed, 120.41 expected, observed/expected ratio (o/e) 1, 90% interval 0.87 to 1.17.
Homologues: Orthologues: chimpanzee PYCARD (99% identical), macaque PYCARD (92% identical), rabbit PYCARD (78% identical), dog PYCARD (76% identical), pig PYCARD (76% identical), mouse Pycard (71% identical), rat Pycard (70% identical), guinea pig PYCARD (65% identical), tropical clawed frog pycard (35% identical), Caenorhabditis elegans ced-3 (16% identical), Drosophila melanogaster Decay (15% identical), Caenorhabditis elegans csp-1 (14% identical), and 3 more. Paralogues in human: PYDC1 (30% identical), CASP8 (19% identical), CASP9 (19% identical), CASP2 (18% identical), CASP5 (18% identical), CASP7 (17% identical), CASP1 (17% identical), CASP3 (16% identical), CASP4 (16% identical), CFLAR (16% identical), CASP12 (15% identical), CASP6 (15% identical), and 4 more.
Diseases named in the same sentence as PYCARD in open-access papers:
PYCARD is named in the same sentence as 96 diseases in open-access papers, as found by Europe PMC text mining. Sharing a sentence is not in itself a finding about the gene and the disease. The quoted sentences say what the papers report.
breast carcinoma (11 papers, 2014 to 2025). "Interestingly, similar associations between PYCARD variations and altered gene expression have been observed in various cancers, including lung cancer, breast cancer, schwannoma tumor, prostate cancer, and pancreatic ductal adenocarcinoma." (PMID 38813354, 2024). "Through searching for the NCBI GEO dataset, the expression of NLRP3, PYCARD, CASP1, and IL-1β genes in the tumor-associated stroma of breast cancer patients were found to be increased with the pathological stage when compared with normal breast stroma." (PMID 38031068, 2023). "The Oncomine database demonstrated that PYCARD was upregulated in bladder cancer, breast cancer, gastric cancer, head and neck cancer, leukemia, lymphoma, liver cancer, and other types of cancers." (PMID 36291776, 2022). "In addition, the silencing of PYCARD after methylation promotes the development of breast cancer, colon cancer, and other tumors." (PMID 32751923, 2020). "In MCF-7 and MDA-MB231 breast cancer cells, small interfering RNA-mediated KAT8 knockdown reduced global H4K16ac levels, silenced the pro-apoptotic gene PYD and CARD domain containing (PYCARD/TMS1/ASC), and inhibited apoptosis." (PMID 40508066, 2025).
glioma (10 papers, 2019 to 2023). A benign or malignant brain and spinal cord tumor that arises from glial cells (astrocytes, oligodendrocytes, ependymal cells). "In gliomas, high expression of PYCARD is related to poor patient prognosis and is used as an independent predictor of chemoresistance." (PMID 35845137, 2022). "In glioma, similarly, ectopic PYCARD expression increased the viability and migration abilities of tumor cells." (PMID 36291776, 2022). "PYCARD is an adaptor protein that assembles the inflammasome, high expression of which was considered to be an independent predictor of unfavorable prognoses in glioma and could promote glioma cell proliferation and migration." (PMID 36823654, 2023). "Therefore, we looked at the expression of differentially expressed genes, ASC/PYCARD, AIM2, and CASP1 under normal and inflammatory conditions in microglia and glioma cells." (PMID 31186453, 2019). "Furthermore, the expression levels of genes encoding NLR proteins (NLRP12, NOD2, NOD1, NLRC4, and NAIP), inflammasome adaptor molecules (PYCARD), and proinflammatory caspases (CASP1, CASP4, and CASP5) were significantly higher in glioma patients than in normal controls." (PMID 31133717, 2019).
melanoma (6 papers, 2019 to 2024). A malignant, usually aggressive tumor composed of atypical, neoplastic melanocytes. "Interestingly, 3 of pyroptosis-associated genes including CASP1, CASP4 and PYCARD, can predict the effectiveness of anti-PD-1 immunotherapy for patients with melanoma." (PMID 36068291, 2022). "Laminaran has a high affinity for PYCARD and has been reported to act as a radiosensitizer and protective agent in melanoma." (PMID 38439022, 2024). "In our bioinformatics and experiment data proved that CASP4 and PYCARD might act as potential biomarkers to predict the effectiveness of anti-PD-1 immunotherapy for melanoma patients." (PMID 36068291, 2022). "Studies disclosed that methylation of genes like APC, PYCARD, and COL11A1 is relevant to the incidence of melanoma, and histone H3K27me3 upregulation can promote melanoma progression." (PMID 36060650, 2022).
psoriasis (6 papers, 2017 to 2024). An autoimmune condition characterized by red, well-delineated plaques with silvery scales that are usually on the extensor surfaces and scalp. "We found that genetic ablations of PYCARD or caspase-1 prevented the development of IMQ-induced psoriasis, highlighting a role in the inflammasome." (PMID 39352743, 2024). "Interestingly, a study of psoriasis-associated changes in the skin transcriptome showed upregulation of PYDC1 and PYCARD in psoriasis lesions." (PMID 29234126, 2017). "All components required for the activation of inflammasomes are found in keratinocytes of psoriasis lesions, and NLR signaling genes NOD2 and PYCARD are upregulated in psoriasis affected epidermis." (PMID 32922182, 2020). "First, we observed a significant increase in the expression of PYCARD (encoding for ASC) and CASP1 (encoding for caspase-1) in the injured skin of patients with psoriasis compared with nonlesioned or healthy control skin groups." (PMID 39352743, 2024). "Furthermore, mRNA of NLRP1, NLRP3, AIM2, PYCARD and CASP1 was observed in both lesional and non-lesional epidermis of psoriasis patients." (PMID 37325658, 2023).
colorectal cancer (5 papers, 2019 to 2025). A primary or metastatic malignant neoplasm that affects the colon or rectum. "Methylation-mediated PYCARD silence helps tumor cells to escape apoptosis in breast and colorectal cancers." (PMID 37501725, 2023). "In contrast, PYCARD was downregulated in colorectal cancer, lung cancer, ovarian cancer, prostate cancer, and sarcoma." (PMID 36291776, 2022). "Recent studies reported higher NLRP3 and PYCARD protein expression in cancer tissues than in adjacent normal tissues from patients with laryngeal squamous cell carcinoma (LSCC) and colorectal cancer (CRC)." (PMID 34540671, 2021).
Clear Cell Renal Cell Carcinoma (4 papers, 2022 to 2024). "This study found that knockdown of PYCARD significantly inhibited the proliferation and invasion of renal clear cell carcinoma." (PMID 38439022, 2024). "We further silenced PYCARD in human renal clear cell carcinoma cell lines 769-P and 786-O cells to investigate the role of PYCARD in renal clear cell carcinoma." (PMID 38439022, 2024). "We designed siRNA for PYCARD to silence PYCARD expression in human renal clear cell carcinoma cell lines 769-P and 786-O cells to investigate the role of PYCARD in renal clear cell carcinoma." (PMID 38439022, 2024). "We found significant differences in PYCARD expression between tumor and normal tissue, particularly in clear cell renal cell carcinoma." (PMID 36291776, 2022). "Finally, we identified natural small molecules that can target PANoptosis-related target proteins by molecular docking and determined the role of PYCARD in renal clear cell carcinoma by in vitro functional assay." (PMID 38439022, 2024). "In addition, we found that down-regulation of PYCARD inhibited the proliferation and migration of renal clear cell carcinoma cells by in vitro functional assays, suggesting that PYCARD could be a novel target for renal clear cell carcinoma therapy." (PMID 38439022, 2024). "In addition, knockdown of PYCARD inhibited the progression of renal clear cell carcinoma cells, suggesting that PYCARD may be a potential target for the treatment of renal clear cell carcinoma." (PMID 38439022, 2024).
lung carcinoma (4 papers, 2008 to 2024). "Similar conclusions were found in lung cancer, while in pancreatic adenocarcinoma, PYCARD expression was increased in 90% of tumor samples compared to adjacent normal tissue, and elevated PYCARD expression was associated with a poorer prognosis." (PMID 36291776, 2022). "Twenty-eight potential biomarker loci were identified and 5 were further examined in lung cancer tissues, yielding two (PAX3 and PYCARD/ASC) that showed frequent hypermethylation." (PMID 18947422, 2008).
pancreatic cancer (4 papers, 2022 to 2024). "A prior study showed that elevated expression of PYCARD contributed to the tumor cell growth and poor prognosis of pancreatic cancer." (PMID 36151761, 2023). "In a pancreatic cancer model, PYCARD silencing inhibited the cell growth, reducing CyclinD1 levels as well." (PMID 35745570, 2022). "It is noteworthy that PYCARD exhibited pro-tumorigenic effects in pancreatic cancer, which suggested that PYCARD specks might communicate with infiltrating immune cells in the tumor microenvironment (TME) and eventually promote tumor progression rather than a pro-apoptotic effect." (PMID 36291776, 2022).
prostate carcinoma (4 papers, 2014 to 2024). A carcinoma that arises from epithelial cells of the prostate gland. "Our present results suggest that promoter hypermethylation of PYCARD can be potentially a tumor-specific biomarker in the clinical setting of prostate cancer." (PMID 33628338, 2021). "We next analyzed methylation statuses in the promoter region of PYCARD in primary prostate cancer specimens." (PMID 33628338, 2021). "Aberrant methylation of PYCARD was detected in a tumor-specific manner in 90% (45/50); these results suggest that the aberrant hypermethylation of PYCARD promoter is frequent in primary prostate carcinomas." (PMID 33628338, 2021). "In order to investigate the biological significance of PYCARD in prostate cancer cells, we first transfected the PYCARDv1-expressing vector into TR15 to produce tetracycline-regulated PYCARDv1-inducible cells." (PMID 33628338, 2021). "We analyzed DNA methylation statuses using 50 microdissected primary prostate cancer tissues and found an extremely high frequency of tumor-specific promoter hypermethylation of PYCARD (90%, 45/50)." (PMID 33628338, 2021). "It has been reported that PYCARD hypermethylation was identified not only in prostate cancer but also in prostate cancer precursor lesions called high-grade prostatic intraepithelial neoplasia (HGPIN)." (PMID 33628338, 2021). "Aberrant promoter hypermethylation of PYCARD along with suppressed protein expression was observed in a stage-specific manner in the great majority of prostate cancer specimens." (PMID 33628338, 2021). "In the 50 prostate cancer specimens we analyzed, PYCARD was hypermethylated in primary prostate cancers in a tumor-specific manner, consistent with previous studies." (PMID 33628338, 2021). "PYCARD is one of such candidates for prostate cancer diagnosis; further analyses are needed to clarify its role and utility value." (PMID 33628338, 2021). "Therefore, we next performed immunohistochemical analyses of FFPE sections from 50 prostate cancer patients using anti-PYCARD antibody to see PYCARD protein expression." (PMID 33628338, 2021). "We first analyzed the expression of PYCARD protein in a normal prostate epithelial cell line RWPE-1 and three prostate cancer cell lines, LNCaP, DU-145, and PC-3." (PMID 33628338, 2021). "Several are known biomarkers for diagnosis and prognosis of prostate cancer (APC, GSTP1, KIT, PYCARD, PGDGRB, RARB, RARRES1, and TIMP1) and some though not biomarkers, were found to be dysregulated in the disease (CDKN1B, MMP7, and MMP9)." (PMID 24626295, 2014). "Immunostaining of PYCARD in the remaining 10 prostate cancer specimens was negative for both normal and tumor cells." (PMID 33628338, 2021). "In most of the primary prostate cancer specimens (72%, 36/50), PYCARD protein was expressed in normal epithelial and/or basal cells, but not in tumor cells." (PMID 33628338, 2021).
COVID-19 (3 papers, 2023 to 2024). A disease caused by infection with severe acute respiratory syndrome coronavirus 2. "From day 0 to day 7, a significant induction of the inflammasome pathway genes, which included NLRC4, NLRP1, CASP1, PYCARD, and IL-18, was detected in COVID-19+ individuals compared to healthy controls." (PMID 38543837, 2024). "For instance, IL1B, NFKB1, NLRP3, PYCARD, and CASP1 are listed in the COVID-19 Disease Map, while there are molecules absent from it, including CCL3, 3L1, 4L2, CXCL1, 2, 3, 5, 16, TNFAIP6, C15orf48, TMEM176A/B, NFE2, PADI4, RAB20, ETS2, PHLDA2, FOLR3, and HP." (PMID 37719701, 2023).
lung adenocarcinoma (3 papers, 2021 to 2025). A carcinoma that arises from the lung and is characterized by the presence of malignant glandular epithelial cells. "PYCARD methylation was particularly associated with later tumor stages of lung adenocarcinoma; only 14% (7 of 50) of stage I but 61% (19 of 31) of later-stage tumors showed methylation." (PMID 33628338, 2021). "However, PYCARD exhibited poor diagnostic efficacy; hence, it is not recommended as a diagnostic marker of lung adenocarcinoma." (PMID 40026444, 2025). "However, PYCARD was significantly lower in COAD (colon adenocarcinoma), KICH (kidney chromophobe), LUAD (lung adenocarcinoma), and PRAD (prostate adenocarcinoma) than in normal tissue." (PMID 36291776, 2022).